ZNF667 (zinc finger protein 667)
Description:
May be involved in transcriptional regulation.
Synonyms: FLJ14011; MIPU1
Tractability: PROTAC: ubiquitination databases record sites on it.
Gene: Protein-coding gene on chromosome 19 (56,438,634 to 56,478,099, reverse strand). Ensembl gene ENSG00000198046.
Subcellular location: Nucleus
Subcellular location (Human Protein Atlas): Nucleoplasm
Pathways (Reactome):
Gene expression (Transcription): Generic Transcription Pathway
Gene Ontology:
Molecular function: protein binding; DNA-binding transcription factor activity; RNA polymerase II cis-regulatory region sequence-specific DNA binding
Biological process: regulation of transcription by RNA polymerase II; negative regulation of transcription by RNA polymerase II; regulation of DNA-templated transcription
Cellular component: nucleus
Genetic constraint (gnomAD): Loss-of-function variants: 20 observed, 39.5 expected, observed/expected ratio (o/e) 0.51, 90% interval 0.35 to 0.74. The upper end of that interval is the gene's LOEUF score, 0.74, which puts it in group 3 of 6, group 1 being the genes least tolerant of losing a copy. Missense variants: 642 observed, 763.94 expected, observed/expected ratio (o/e) 0.84, 90% interval 0.79 to 0.9. Synonymous variants: 228 observed, 261.12 expected, observed/expected ratio (o/e) 0.87, 90% interval 0.78 to 0.97.
Homologues: Orthologues: chimpanzee ZNF667 (99% identical), macaque ZNF667 (96% identical), pig ZNF667 (76% identical), rat Zfp667 (76% identical), mouse Zfp667 (74% identical), guinea pig ZNF667 (67% identical), Drosophila melanogaster CG11902 (26% identical), zebrafish znf574 (23% identical), Drosophila melanogaster CG10631 (22% identical), Drosophila melanogaster CG11696 (16% identical). Paralogues in human: ZNF671 (32% identical), ZNF865 (27% identical), ZNF662 (25% identical), ZNF710 (19% identical), ZNF366 (19% identical), ZNF783 (12% identical), ZNF212 (12% identical).
Diseases named in the same sentence as ZNF667 in open-access papers:
ZNF667 is named in the same sentence as 14 diseases in open-access papers, as found by Europe PMC text mining. Sharing a sentence is not in itself a finding about the gene and the disease. The quoted sentences say what the papers report.
ischemia (2 papers, 2009 to 2014). A hypoperfusion of the BLOOD through an organ or tissue caused by a PATHOLOGIC CONSTRICTION or obstruction of its BLOOD VESSELS, or an absence of BLOOD CIRCULATION. "Collectively, our present study demonstrated that ZNF667 is a novel direct regulator of the rat Bax gene and a protective protein in cardiomyocytes, which has the potential to protect the rat heart against ischemia/reperfusion injury." (PMID 25397408, 2014).
laryngeal squamous cell carcinoma (2 papers, 2019 to 2023). A squamous cell carcinoma that arises from the larynx. "In a study on laryngeal squamous cell carcinoma (LSCC), it was found that ZNF667 is a tumor-suppressing gene." (PMID 37889708, 2023).
brain astrocytoma (1 paper, 2014). A astrocytoma (excluding glioblastoma) that involves the brain. "Interestingly, it was also found that human ZNF667 was indeed upregulated in human brain astrocytomas." (PMID 25397408, 2014).
esophageal squamous cell carcinoma (1 paper, 2021). Esophageal squamous cell carcinoma (ESCC) is a type of esophageal carcinoma (EC) that can affect any part of the esophagus, but is usually located in the upper or middle third. "ZNF667, encoding Zinc finger protein 667, may involve in transcription regulation, the aberrantly hypermethylation of which promoted progression of laryngeal and esophageal squamous cell carcinoma." (PMID 33485349, 2021).
hepatocellular carcinoma (1 paper, 2019). A malignant tumor that arises from hepatocytes. "Recently, it was reported that ZNF667 served as a putative oncogene in human hepatocellular carcinoma." (PMID 30684967, 2019).
lymphoid neoplasm (1 paper, 2021). A neoplasm composed of a lymphocytic cell population which is usually malignant (clonal) by molecular genetic and/or immunophenotypic analysis. "The expression was significantly differential across various types of lymphoid neoplasms for HELQ/EGR3/ZNF667." (PMID 33485349, 2021). "Moreover, HELQ, EGR3 and ZNF667 were expressed differentially among diverse types of lymphoid neoplasm." (PMID 33485349, 2021).
pancreas cancer (1 paper, 2022). "The ZNF667 protein was also less abundant in the pancreas cancer cell lines compared to that in control cell lines." (PMID 35165277, 2022).
Richter syndrome (1 paper, 2021). Transformation of chronic lymphocytic leukemia into aggressive non-Hodgkin's lymphoma, usually diffuse large B-cell lymphoma (immunoblastic or centroblastic variant). "HELQ expression was found to be related with response of immunochemotherapy treatment significantly (p = 0.0413), while HELQ and ZNF667 were expressed differently between stable CLL and Richter syndrome patients (p < 0.0001 and p = 0.0278, respectively)." (PMID 33485349, 2021).
cancer (5 papers, 2014 to 2026). A tumor composed of atypical neoplastic, often pleomorphic cells that invade other tissues. "Among these, CpG sites associated with ZNF667, TEAD1, HDAC4, MSI2, and CCM2 were predominantly hypermethylated, while malignant tumors overall exhibited lower methylation levels compared to the benign group." (PMID 41597272, 2026). "Through in-depth integrated analyses, a set of novel candidate biomarkers were identified, including ZNF667 and ZNF667-AS1, whose expressions were linked to a better prognosis for PDAC patients by affecting the proliferation of cancer cells." (PMID 35165277, 2022). "Of course, the roles of ZNF667 in cancer need to be deeply elucidated in the future." (PMID 25397408, 2014). "On the other hand, we also evaluated apoptosis after overexpressing ZNF667 and ZNF667-AS1 in both cancer cell lines." (PMID 35165277, 2022). "Together, these results indicated that ZNF667 and ZNF667-AS1 both suppress tumorigenesis of PDAC via suppressing proliferation but not via promoting apoptosis of cancer cells." (PMID 35165277, 2022).
tumor (4 papers, 2020 to 2023). "Therefore, ZNF667 may be a novel biomarker for predicting aggressive tumor subtype in Middle Eastern CRC and may serve as a potential therapeutic target for CRC." (PMID 34785764, 2021).
neurodegenerative disease (1 paper, 2020). A disorder of the central nervous system characterized by gradual and progressive loss of neural tissue and neurologic function. "These enriched TFs displayed maximum interactions with their target genes (GPR50, ABCC9, ZNF667 and CALB1) and could prove relevant to several neurodegenerative diseases." (PMID 32967368, 2020).
ZNF667 also shares sentences with these, for which no sentence is quoted: myocardial ischemia (3 papers); metastatic tumor (1); myocardial infarction (1).